ZDHHC19 (zDHHC palmitoyltransferase 19)
Description:
Palmitoyltransferase that mediates palmitoylation oproteins, such as RRAS and SQSTM1. Catalyzes palmitoylation of RRAS, leading to increased cell viability. Acts as a positive regulator of autophagy by mediating palmitoylation of SQSTM1, promoting affinity between SQSTM1 and ATG8 proteins and recruitment of ubiquitinated cargo proteins to autophagosomes. Palmitoyltransferase activity may be crucial for spermatogenesis (By similarity). (Microbial infection) Promotes Chikungunya virus (CHIKV) replication by mediating viral nsp1 palmitoylation.
Synonyms: MGC33345; DHHC19
Tractability: Antibody: UniProt predicts a signal peptide or a membrane-spanning region.
Gene: Protein-coding gene on chromosome 3 (196,197,452 to 196,211,437, reverse strand). Ensembl gene ENSG00000163958.
Subcellular location: Golgi apparatus membrane; Cytoplasm, perinuclear region; Cell membrane
Gene Ontology:
Molecular function: protein-cysteine S-palmitoyltransferase activity; palmitoyltransferase activity
Biological process: peptidyl-L-cysteine S-palmitoylation; positive regulation of aggrephagy; protein targeting to membrane
Cellular component: endoplasmic reticulum; Golgi membrane; perinucleolar compartment; plasma membrane; perinuclear region of cytoplasm
Genetic constraint (gnomAD): Loss-of-function variants: 30 observed, 33.77 expected, observed/expected ratio (o/e) 0.89, 90% interval 0.66 to 1.21. The upper end of that interval is the gene's LOEUF score, 1.21, which puts it in group 5 of 6, group 1 being the genes least tolerant of losing a copy. Missense variants: 364 observed, 387.98 expected, observed/expected ratio (o/e) 0.94, 90% interval 0.86 to 1.02. Synonymous variants: 178 observed, 155.76 expected, observed/expected ratio (o/e) 1.14, 90% interval 1.01 to 1.29.
Homologues: Orthologues: chimpanzee ZDHHC19 (98% identical), macaque ZDHHC19 (90% identical), pig ZDHHC19 (83% identical), rabbit ZDHHC19 (77% identical), dog ZDHHC19 (77% identical), mouse Zdhhc19 (68% identical), rat Zdhhc19 (68% identical), guinea pig ZDHHC19 (64% identical), Caenorhabditis elegans dhhc-8 (26% identical). Paralogues in human: ZDHHC1 (23% identical), ZDHHC14 (22% identical), ZDHHC3 (20% identical), ZDHHC18 (20% identical), ZDHHC7 (19% identical), ZDHHC9 (19% identical), ZDHHC12 (18% identical), ZDHHC4 (18% identical), ZDHHC11 (18% identical), ZDHHC11B (18% identical), ZDHHC15 (17% identical), ZDHHC20 (17% identical), and 5 more.
Diseases named in the same sentence as ZDHHC19 in open-access papers:
ZDHHC19 is named in the same sentence as 25 diseases in open-access papers, as found by Europe PMC text mining. Sharing a sentence is not in itself a finding about the gene and the disease. The quoted sentences say what the papers report.
Sepsis (6 papers, 2020 to 2025). Sepsis is defined as life-threatening organ dysfunction caused by a dysregulated host response to infection. "One of the most noteworthy findings of this study is the observed association between ZDHHC19 expression and clinical severity in sepsis." (PMID 40666706, 2025). "Despite considerable progress in understanding the role of ZDHHC19 in sepsis, the molecular mechanisms underlying its induction remain elusive." (PMID 40282319, 2025). "This study aimed to confirm the molecular diagnostic value of ZDHHC19 plasma levels for early sepsis diagnosis, disease progression monitoring, and severity assessment." (PMID 40282319, 2025). "This study addresses this gap by integrating single-cell transcriptomics, machine learning, and cell communication analysis to investigate the expression patterns, immune associations, and prognostic relevance of ZDHHC19 in sepsis." (PMID 40666706, 2025). "Given that miRNAs bind in a sequence-specific manner, we also raised the question of whether common single nucleotide polymorphisms affecting miRNA binding sites might influence ZDHHC19 levels and clinical parameters in sepsis." (PMID 40282319, 2025). "Additionally, ZDHHC19 expression was linked to poor patient prognosis, with higher levels correlating with increased mortality and sepsis shock." (PMID 40666706, 2025). "Our findings also reveal that ZDHHC19 expression was associated with the activation of multiple inflammatory pathways, including collagen metabolism, myeloid cell activation, and cell adhesion, which contribute to the progression of sepsis." (PMID 40666706, 2025). "Expression of ZDHHC19 has been associated with sepsis and septic shock in previous human studies." (PMID 34442377, 2021). "Therefore, understanding the role of ZDHHC19 and its associated palmitoylation activity in immune cells during sepsis could provide valuable insights into the pathophysiology of sepsis." (PMID 40666706, 2025). "ZDHHC19 is part of the 29-mRNA panel used in the InSep test to detect transcriptomic signatures characteristic of acute infection and sepsis." (PMID 40282319, 2025). "In this study, we investigated the expression and functional role of ZDHHC19, a palmitoyltransferase enzyme, in sepsis." (PMID 40666706, 2025). "Among the 23 ZDHHC isoforms, ZDHHC19 has been reported to be induced in severe infections and under septic conditions, making it a potential sepsis biomarker." (PMID 40282319, 2025). "In our study, we found that ZDHHC19 expression was particularly high in neutrophils, which are central to the pathophysiology of sepsis due to their role in the early inflammatory response and host defense." (PMID 40666706, 2025). "In patients with sepsis, ZDHHC19 expression was significantly elevated compared to the infection group, especially in urogenital sepsis." (PMID 40282319, 2025). "By focusing on its role in neutrophil activation, immune signaling, and disease severity, our findings provide new insights into the molecular mechanisms driving immune dysregulation in sepsis and propose ZDHHC19 as a potential mediator of disease progression." (PMID 40666706, 2025). "Earlier studies provided clear-cut evidence that plasma levels of ZDHHC19 are elevated in sepsis, but there is scarce information on factors responsible for upregulation of ZDHHC19 expression at the transcriptional and post-transcriptional levels." (PMID 40282319, 2025). "Our findings demonstrate that ZDHHC19 is significantly upregulated in sepsis, particularly in neutrophils, and that its expression correlates with key inflammatory responses and immune cell communication." (PMID 40666706, 2025). "To investigate the potential role of microRNAs in the regulation of ZDHHC19 expression in sepsis, we first needed a comprehensive list of miRNAs that potentially bind to the gene’s mRNA." (PMID 40282319, 2025).
Sepsis (continued). "In this discussion, we compare our findings with previous studies and explore the broader context of ZDHHC19's role in sepsis and its potential therapeutic implications." (PMID 40666706, 2025). "Furthermore, ZDHHC19 demonstrated excellent diagnostic performance, with an AUC above 0.7 in the ROC curve for all four datasets, with the largest AUC reaching 0.871, suggesting that ZDHHC19 could be a promising diagnostic molecular marker for sepsis." (PMID 40666706, 2025). "The upregulation of ZDHHC19 in sepsis shock patients and its correlation with poor survival outcomes highlight its potential as a marker of disease severity." (PMID 40666706, 2025). "The crucial role of ZDHHC19 in stabilizing signaling and metabolic networks in sepsis is particularly intriguing, given its broad range of substrates and interaction partners." (PMID 40282319, 2025). "Overall, this study provides experimental evidence that miRNAs, particularly miR-4733-3p and miR-596, are involved in the regulation of ZDHHC19 in sepsis." (PMID 40282319, 2025). "For instance, ZDHHC19 expression in sepsis should primarily be up-regulated at the transcriptional level." (PMID 40282319, 2025). "Future studies involving functional assays and in vivo models are necessary to substantiate these findings and assess the therapeutic potential of targeting ZDHHC19 in sepsis." (PMID 40666706, 2025). "Feature importance scoring for the eight differential palmitoylation-related genes across four sepsis datasets consistently showed ZDHHC19 ranked highest." (PMID 40666706, 2025). "We found that ZDHHC19 was upregulated in sepsis shock patients and correlated with poor survival outcomes, suggesting its potential utility as a prognostic indicator." (PMID 40666706, 2025). "At the expression level, ZDHHC19 was found to be highly expressed in sepsis patients across all four datasets." (PMID 40666706, 2025). "Our results demonstrate that ZDHHC19 is significantly upregulated in neutrophils during sepsis and correlates with inflammatory pathways critical to disease progression." (PMID 40666706, 2025). "This study explores the expression and functional significance of ZDHHC19 in sepsis, focusing on its involvement in immune cell activation, inflammatory pathways, and its potential as a diagnostic and prognostic biomarker." (PMID 40666706, 2025). "The parallels between cancer and sepsis, particularly the dysregulated immune response and inflammation, highlight the relevance of investigating ZDHHC19 in the context of sepsis." (PMID 40666706, 2025). "Previous studies have shown that ZDHHC19 influences immune cell signaling and function, but its role in sepsis, particularly its impact on immune cell subsets and inflammatory pathways, is not yet fully understood." (PMID 40666706, 2025). "Sepsis induces an immunosuppressive milieu, and previous studies indicate ZDHHC19's role in Smad3 palmitoylation, activating the TGF-β pathway." (PMID 38167131, 2024). "Seeking insights from diverse clinical contexts emphasizes the need to unravel ZDHHC19's mechanisms in platelet function and its potential impact on sepsis progression." (PMID 38167131, 2024). "Considering sepsis severity gradients, exploring the link between ZDHHC19 in platelets and disease gravity becomes crucial." (PMID 38167131, 2024). "ZDHHC19 showed the lowest expression in Platelets of healthy individuals, increased expression in Platelets of sepsis survivors at 28 days, and the highest expression in Platelets of sepsis non-survivors at 28 days." (PMID 38167131, 2024). "These shared few commonalities between the different disease groups with the exception of DDAH2, RGL4, and ZDHHC19 in adult sepsis and pediatric septic shock." (PMID 32318053, 2020). "Understanding how ZDHHC19 alters immune responses in both cancer and sepsis may offer new avenues for developing immunomodulatory therapies aimed at restoring immune balance and improving clinical outcomes." (PMID 40666706, 2025).
Sepsis (continued). "The upregulation of ZDHHC19 in neutrophils suggests that palmitoylation pathways may be critical in regulating neutrophil activation and function during sepsis, in line with findings showing that palmitoylation affects neutrophil behavior." (PMID 40666706, 2025). "Furthermore, our study showed that ZDHHC19-positive neutrophils had the highest communication with macrophages, another key immune cell type in sepsis." (PMID 40666706, 2025). "In conclusion, our study provides strong evidence that ZDHHC19 plays a significant role in the immune response during sepsis, particularly in neutrophils, and may serve as a novel diagnostic and prognostic biomarker for the disease." (PMID 40666706, 2025). "Our study suggests that targeting ZDHHC19-mediated signaling pathways could modulate the inflammatory response in sepsis." (PMID 40666706, 2025). "Nevertheless, an inverse correlation between mRNA and miRNA levels implies that upregulation of ZDHHC19 transcript levels might partly be attributed to reduced miR-4733-3p and miR-592 expression in sepsis." (PMID 40282319, 2025). "This suggests that while these SNPs may alter miRNA binding, their subtle, direct impact on ZDHHC19 expression in sepsis is likely overshadowed by stronger molecular factors mediating inflammatory responses and organ dysfunction." (PMID 40282319, 2025). "Given the importance of MHC II molecules in sepsis, this suggests that ZDHHC19 may promote disease progression." (PMID 40666706, 2025). "The observation that ZDHHC19 was highly expressed in CD177+ neutrophils suggests that this subset may be particularly involved in the inflammatory processes of sepsis." (PMID 40666706, 2025). "ZDHHC19 was highly expressed in sepsis shock patients across three datasets, indicating that its high expression may contribute to disease progression." (PMID 40666706, 2025). "Given the importance of immune cells in sepsis, especially neutrophils, macrophages, and T cells, studying the expression and function of ZDHHC19 in these cells may offer novel therapeutic targets for sepsis management." (PMID 40666706, 2025). "By regulating the activation of CD177+ neutrophils, ZDHHC19 may influence the severity of the immune response during sepsis and contribute to disease progression." (PMID 40666706, 2025). "In sepsis, increased ZDHHC19 in platelets might modulate TGF-β signaling, impacting immune responses." (PMID 38167131, 2024). "Further exploration of the intricate interplay between ZDHHC19, platelets, and the immune response could unveil novel therapeutic targets for attenuating sepsis severity and improving patient outcomes." (PMID 38167131, 2024). "This dynamic profile prompts questions about ZDHHC19's role in platelet function during sepsis." (PMID 38167131, 2024). "We found it to be associated to adult SIRS (along with ZDHHC18, as opposed to ZDHHC19 found in the sepsis pathway association analysis)." (PMID 32318053, 2020). "The inverse relationship between ZDHHC19 and miRNA expression suggests that dysregulation of miRNA levels may contribute to the pathological upregulation of ZDHHC19 in sepsis, providing a potential avenue for therapeutic interventions aimed at modulating miRNA expression to control ZDHHC19 levels." (PMID 40282319, 2025). "In contrast, ZDHHC19 may reflect more specific aspects of immune dysregulation in sepsis." (PMID 40666706, 2025). "Moreover, understanding the molecular pathways and cellular networks regulated by ZDHHC19 could contribute to the development of targeted therapies that modulate immune responses in sepsis, similar to cancer immunotherapies that aim to restore immune system function." (PMID 40666706, 2025). "Overall, ZDHHC19 may accelerate the inflammatory response by promoting the aggregation of immune-inflammatory cells, while simultaneously downregulating antibacterial responses, such as antigen presentation and interferon responses, thus contributing to the progression of sepsis." (PMID 40666706, 2025).
Sepsis (continued). "A notable finding of our study was the high specificity of ZDHHC19 expression in CD177+ neutrophils, a subset of neutrophils involved in the pathogenesis of sepsis." (PMID 40666706, 2025). "We identified significant upregulation of NTSR1, BCL6, ZDHHC19, MGLL, and ALPK1 in sepsis compared to healthy individuals, while VAV2 and SATB1 were significantly downregulated in sepsis." (PMID 38167131, 2024). "In adult sepsis, genes TDRD9, GPR84, and CD177 interacted via overlapped genes EXOSC4 (TDRD9 ↔ GPR84 ↔ CD177), ZDHHC19 (TDRD9 ↔ CD177) and NECAB1 (GPR84 ↔ CD177)." (PMID 32318053, 2020). "Gene entities shared between sepsis and severe sepsis response hubs are; TDRD9 – LIN7A, GPR84 – ENTPD7, PYCT1A and ZDHHC19, CD177 – DDAH2 and RGL4, SLC16A3 – DENND3 and MBD6, MYL9 – CMTM5, ITGB3, ITGA2B, NRGN, SELP and TREML1." (PMID 32318053, 2020). "The lack of comprehensive data on how ZDHHC19 modulates innate immune responses, especially in neutrophils—key effector cells in sepsis—represents a significant gap in current knowledge." (PMID 40666706, 2025). "While ZDHHC19’s specific role in inflammation and sepsis is not well-studied, protein palmitoylation has been implicated in immune cell function and inflammatory signaling pathways." (PMID 38167131, 2024). "Furthermore, the high specificity of ZDHHC19 expression in CD177+ neutrophils suggests this enzyme may play a critical role in neutrophil activation and inflammation during sepsis." (PMID 40666706, 2025). "The observed significant upregulation of NTSR1, BCL6, ZDHHC19, MGLL, and ALPK1 in sepsis compared to healthy individuals, along with the notable downregulation of VAV2 and SATB1 in sepsis, provides a comprehensive picture of the altered gene expression landscape during sepsis." (PMID 38167131, 2024). "Moreover, while several DHHC family members have been studied in cancer and neurological disorders, their specific contributions to sepsis pathophysiology remain poorly understood, and ZDHHC19, in particular, has not been systematically explored in this context." (PMID 40666706, 2025). "Regarding sepsis mortality at 28 days, we observed that ZDHHC19 had the lowest expression in Platelets of healthy individuals, increased expression in Platelets of sepsis survivors at 28 days, and the highest expression in Platelets of sepsis non-survivors at 28 days." (PMID 38167131, 2024). "In our study, ZDHHC19 exhibited a distinct expression pattern in platelets, showing the lowest levels in healthy individuals, increased expression in platelets of sepsis survivors at 28 days, and the highest expression in platelets of sepsis non-survivors at 28 days." (PMID 38167131, 2024). "Additionally, bulk RNA analysis revealed significant increases in NTSR1, BCL6, ZDHHC19, MGLL, and ALPK1 in sepsis, and significant decreases in VAV2 and SATB1 in sepsis; FCHO1 showed a significant decrease in sepsis patients who did not survive compared to those who survived at 28 days." (PMID 38167131, 2024).
osteosarcoma (3 papers, 2022 to 2023). A usually aggressive malignant bone-forming mesenchymal neoplasm, predominantly affecting adolescents and young adults. "In osteosarcoma, the most frequent malignant primary bone tumor in children and young adults, ZDHHC19 was found to be highly expressed, and knockdown of ZDHHC19 led to downregulated expression of Wnt/β-catenin." (PMID 37759431, 2023).
acute respiratory distress syndrome (2 papers, 2021 to 2025). Progressive and life-threatening pulmonary distress in the absence of an underlying pulmonary condition, usually following major trauma or surgery. "A fivefold upregulation of ZDHHC19 expression has been observed in patients with acute respiratory distress syndrome (ARDS)." (PMID 40282319, 2025). "In a previous study, both ZDHHC19 and FOXC1 were found to be upregulated more than five times in neutrophils from patients with acute respiratory distress syndrome (ARDS) than in neutrophils from healthy volunteers." (PMID 33717105, 2021).
cervical cancer (2 papers, 2023 to 2024). A primary or metastatic malignant neoplasm involving the cervix. "ZDHHC19 exhibits elevated expression in malignant cervical cancer tissues, consequently driving cervical cancer cells EMT, migration, and invasion." (PMID 38233791, 2024).
adrenocortical carcinoma (1 paper, 2025). "Regarding chemokine receptors, ZDHHC19 displayed a generally positive correlation with chemokine receptors in most cancers, except for adrenocortical carcinoma, endometrial carcinoma, uterine sarcoma, and uveal melanoma, where it was negatively correlated with chemokine receptors." (PMID 40666706, 2025).
axonal neuropathy (1 paper, 2007). Any nerve disorder affecting the axon of a nerve. "These include the NRM (nurim [nuclear envelope membrane protein]), ZDHHC19 (zinc finger, DHHC-type containing 19), UCP2 (uncoupling protein 2 [mitochondrial, proton carrier]) and GAN (giant axonal neuropathy [gigaxonin]) genes." (PMID 17974019, 2007).
bladder cancer (1 paper, 2025). "Box plots and paired box plots showed that ZDHHC19 was significantly upregulated in most cancer types, including bladder cancer and breast cancer, indicating that ZDHHC19 acts as a common oncogene." (PMID 40666706, 2025).